KRAS (KRas proto-oncogene, GTPase)
Diseases named in the same sentence as KRAS in open-access papers (continued):
Sharing a sentence is not in itself a finding about the gene and the disease.
cancer (continued). "The most common downregulated pathways in cancer were bile acid metabolism, which was downregulated in 13 site-specific cancers, and KRAS signaling." (PMID 34203763, 2021). "The results of this line of the investigation show that a significant reduction in SLUG led to an upregulation or sustained expression of E-cadherin in two of the three cancer cell lines when oncogenic KRAS was turned off." (PMID 34145248, 2021). "Activated KRAS binds and activates RAF family kinases (RAF1, BRAF, and ARAF), subsequently leading to uncontrolled proliferation and other processes causing cancer development and spread." (PMID 35141142, 2021). "This potential central role of PKM2 in KRAS mutant cancer cells was studied through time course simulations where either PKM2 or c-Myc were systematically downregulated in cancer, while they were separately upregulated in physiological conditions." (PMID 33925206, 2021). "In particular, artesunate, one of the most popular artemisinins, can trigger ferroptosis in KRAS-mutant PDA cancer cells by increasing the intracellular levels of free iron." (PMID 34485382, 2021). "Despite this high genetic diversity, mutation and activation of the KRAS oncogene is almost always required for the initiation of PanINs, with KRAS mutations found in 90% of all PDAC samples, driving cancer cell proliferation and survival." (PMID 34298706, 2021). "A classic example is KRAS, which is essential to many cancers but until recently has been considered ‘undruggable’." (PMID 33554860, 2021). "The members of the rat sarcoma (RAS) viral oncogene family, which include HRAS, KRAS, and NRAS, are the most commonly mutated oncogenes in human cancers." (PMID 34484567, 2021). "KRAS mutation is among the most prominent molecular markers in metastatic CRC patients, and mutations of KRAS render cells responsive to anti-cancer therapy such as anti-EGFR antibody treatment." (PMID 33971967, 2021). "Results of GSEA analysis also revealed the associations of GGH with other cancer-related molecular pathways, including DNA replication, cell cycle, MAPK, KRAS, STAT3, and B cell receptor." (PMID 35082830, 2021). "Pancreatic stellate cells and mutant KRAS cancer cells have a synergistic effect on the immune microenvironment." (PMID 33777798, 2021). "The pharmacological inhibition of IGF-1R signaling led to a substantial eradication of residual disease and a significant delay in cancer recurrence in response to the reactivation of KRAS or c-MYC." (PMID 34491463, 2021). "KRAS is the most frequently mutated of the RAS isoforms, accounting for up to 86% of RAS mutant cancer cases." (PMID 34830912, 2021). "The major representatives of the RAS gene family, namely HRAS, KRAS and NRAS, are the most frequently mutated genes in malignant neoplasms, and have been under the spotlight of scientific research for the development of targeted therapies." (PMID 34948093, 2021). "In this study, a modified G12A-K-ras epitope (139A) with sequence-specific modifications to improve immunogenicity was developed as a potential vaccine against G12A-mutant KRAS cancers." (PMID 33652552, 2021). "In contrast to other oncogenic proteins activated in cancer and despite multiple attempts to harness it, KRAS was considered undruggable for a long time." (PMID 35096591, 2021). "Both these kinases were previously identified as critically important for KRas-dependent cancer cells." (PMID 34955846, 2021). "We show that KRAS-ablated cancer cells retain substantial tumorigenic capacity; however, they fail to evade the host immune system, triggering strong antitumor effects." (PMID 33674596, 2021). "Genetic depletion or pharmacological inhibition with sulfasalazine or HG106 markedly induced the cell death of KRAS-mutant cancer cells in vitro and tumor growth suppression in vivo." (PMID 34722530, 2021).
cancer (continued). "Given that KRAS mutations are found in nearly all of the PDAC, this cancer type is arguably the most RAS-addicted cancer." (PMID 34298594, 2021). "Across a broad range of human cancers, gain-of-function mutations in RAS genes (HRAS, NRAS, and KRAS) lead to constitutive activity of oncoproteins responsible for tumorigenesis and cancer progression." (PMID 34607583, 2021). "In accordance with this, KYA1797K demonstrated significant effectiveness against KRAS-driven cancer in KrasLA2 mice via inhibiting the Ras-ERK pathway." (PMID 34769090, 2021). "The concordance rate of KRAS status between cancer tissue and ctDNA has been reported as 75–96%25–27, because the measurement of gene mutations in tissue has a problem of heterogeneity." (PMID 33432066, 2021). "Despite the structural liabilities identified by us, the peptides described herein represent valuable templates for achieving in vivo activity against KRAS-driven, non-G12C cancers." (PMID 35024121, 2021). "Nevertheless, the peptides described in this report represent a valuable scaffold for the genesis of novel validated inhibitors of KRAS signaling in cancer patients unserved by current successes with covalent G12C inhibition." (PMID 35024121, 2021). "Activated KRAS and its downstream effectors were involved in blocking endoplasmic reticulum (ER) stress-induced cell death in cancers." (PMID 33466836, 2021). "In primary CRC, the prognostic value of KRAS has been suggested to be limited to MSS cancers and to depend on the consensus molecular subtypes." (PMID 33325154, 2021). "Mutations affecting members of the RAS family genes (KRAS, HRAS, NRAS) are the most frequent genetic alterations in human cancers accounting for about 27% of all tumors." (PMID 33777798, 2021). "Next, we tested the PHASIFY method in 91 clinical plasma samples from 34 unique patients collected at different time points with diverse advanced cancers and BRAF, KRAS or NRAS mutations." (PMID 34608196, 2021). "Mutations affecting members of the RAS family genes (KRAS, HRAS, NRAS) are the most frequent genetic alterations in human cancer, affecting about 27% of all tumors, including lung, colorectal and pancreatic ductal adenocarcinoma, among others." (PMID 35096591, 2021). "This increase in ROS is essential to drive the formation and progression of KRAS‐mutant cancer by upregulating survival and growth factor signaling and generating mitochondrial DNA mutations." (PMID 34369083, 2021). "To assess the functional relevance of the oncogenic KRAS isoforms in human cancer cell lines in vitro, we carried out shRNA-mediated knockdown of each isoform in KRAS mutant cancer cell lines A549, SUIT2, YAPC, and H358." (PMID 34257283, 2021). "RAS genes (HRAS, KRAS, and NRAS) comprise the most frequently mutated oncogene family in human cancer." (PMID 34298594, 2021). "Among them, KRAS 4B has long been considered the main isoform due to its wide and high expression in human cancers." (PMID 34742312, 2021). "Mutant KRAS is prevalent in lung, colon, and pancreatic cancers, making it one of the most aggressive and deadliest cancers in the US." (PMID 34830912, 2021).
cancer (continued). "70% of patients had coamplifications of receptor tyrosine kinase or other cancer-promoting genes, including MET, KRAS, FGFR1, IGFR1, SRC and VEGFA18–20, potentially associated with resistance to EGFR-inhibitors." (PMID 33199443, 2021). "The system has been tested in various forms to deplete the KRAS function in different cancer cells and animal models." (PMID 34781949, 2021). "Compound 1 had a visibly lower activity, yet the activity profile seemed to correlate with the KRAS dependence of the cancer cell lines." (PMID 34307350, 2021). "Exosomes are cell-derived nanovesicles, and lately, cancer-derived exosomes have been reported to carry KRAS protein, which contributes to the malignancy of many cancers." (PMID 33466836, 2021). "The current study reports on the optimization of the PCAIs and the determination of their mechanisms of action in KRAS-mutant cancer cells." (PMID 34830912, 2021). "The most frequent mutated oncogene family in the history of human cancer is the RAS gene family, including NRAS, HRAS, and, most importantly, KRAS." (PMID 34638560, 2021). "LY3214996 is being used with abemaciclib, hydroxychloroquine, or RMC-4630, in solid tumors, including KRAS-mutant cancers." (PMID 34607583, 2021). "With a pressing need for different approaches for KRAS-mutant cancers, here we describe a new drug for this indication." (PMID 33130216, 2021). "Despite long and persistent efforts, therapeutic targeting of KRAS‐mutant cancer has remained a significant challenge in clinical oncology." (PMID 34369083, 2021). "Primary outcome measurement is enrichment of RAS (KRAS, NRAS and HRAS) alterations in BRAF variant cancers." (PMID 33507258, 2021). "Histological examination of these tumors, which we call KRAS-dep and KRAS-indep, showed well, moderately or poorly differentiated carcinomas." (PMID 33674596, 2021). "Of the 50 successfully tested carcinomas, EGFR mutations were identified in 16 cases (32%; two in exon 18, four in exon 19, two in exon 20, eight in exon 21), and KRAS mutations were identified in two (4%; two exon 2)." (PMID 33602172, 2021). "The clinical failure of agents against the RAF/MEK/ERK pathway downstream of RAS in KRAS mutant cancers has led to explore the possibility of using combinations of targeted agents inhibiting the multiple pathways downstream of RAS." (PMID 32560574, 2020). "It is highly possible that MB21D2 overexpression or Q311E mutation serves as a secondary regulatory loop to control PI3K activity during cell transformation and cancer development through KRAS upregulation." (PMID 32979859, 2020). "CM-MIR143#12 shows anticancer effects by impairing the KRAS signaling networks in many kinds of cancer." (PMID 33182548, 2020). "A higher than expected number of KRAS and EGFR mutations were observed among adenocarcinoma cases, with fewer than expected among squamous cell and other cancer types (p-value of <0.0001)." (PMID 32756609, 2020). "MRTX 894 also locks KRAS in an inactive GDP-bound state and blocks the KRAS-dependent signal transduction and cancer cell viability." (PMID 32548736, 2020).
cancer (continued). "Even though KRAS has been known as a significant driver in various cancers, it has long been considered undruggable." (PMID 33412753, 2020). "At last, we cover novel therapeutic approaches that target KRAS-induced inflammation and immune-modulatory mechanisms in cancer and review the agents currently being investigated in clinical trials." (PMID 33116132, 2020). "Few therapies are currently available for patients with KRAS-driven cancers, highlighting the need to identify new molecular targets that modulate central downstream effector pathways." (PMID 31874105, 2020). "Small-molecule inhibitors against the downstream effectors of KRAS, such as MEK, demonstrated only limited antitumour activity in KRAS-mutated (KRASm) cancers as well." (PMID 32147669, 2020). "The forthcoming results will provide important insights on the safety and tolerability of these combinations in KRAS-mutant cancers." (PMID 33116132, 2020). "The fasting-mimicking diet selectivity reverses vitamin C-induced up-regulation of heme-oxygenase-1 and ferritin in KRAS-mutant cancer cells, consequently increasing reactive iron, oxygen species, and cell death; an effect further potentiated by chemotherapy." (PMID 32393788, 2020). "Our results also showed that the cancer cell-selective toxicity of AA was dependent on ROS, which is consistent with an increase of the mitochondrial-derived ROS in KRAS and BRAF mutant cells." (PMID 33071784, 2020). "Vaccines under development are designed to intervene with immune components of the TME, secreted proteins (mucins), as well as proteins expressed by cancer cells which directly or indirectly facilitate PDAC invasiveness (KRAS and kinesins)." (PMID 33050151, 2020). "We also previously reported a KRAS mutant cancer cell line HUP-T3 with FGFR-driven feedback activation following selumetinib treatment, which can be inhibited by 5 μM SHP099." (PMID 32076487, 2020). "Stable isotope tracer studies in KRAS mutant cancer cells have demonstrated that glutamine supports tumorigenesis by supplying carbon and nitrogen required for biomass synthesis." (PMID 32266129, 2020). "The successful synthesis of these tracers has been undertaken utilizing boronic ester radio-fluorination methods and will allow for investigation of Oncrasin based molecules as potential diagnostics for cancers expressing mutant KRAS protein." (PMID 33169204, 2020). "Another possibility is to identify subsets of cancers that are exquisitely sensitive to glucose deprivation, such as the double mutants of KRAS and KEAP1, which have been shown to be dependent on GLUT8 activity." (PMID 32517099, 2020). "RAS proteins play a causal role in human cancer, and the widespread prevalence of RAS mutations (KRAS, NRAS, HRAS) in human cancer has been recognized for many years." (PMID 32100402, 2020). "In several types of cancer, including mutant KRAS lung tumors, an important part of this effect has been attributed to the enhanced activity of COX1 and 2, the enzymes responsible for the production of prostaglandins from AA." (PMID 32034305, 2020). "This concept is important to be considered in therapeutic approaches targeting licensing and replication components in KRAS mutant cancers yet is likely to provide a vulnerability for therapies inducing replication stress." (PMID 32612138, 2020).
cancer (continued). "Consistent with the increase in ferrous iron, we found that STS, alone or in combination with vitamin C, downregulated FTH protein expression selectively in KRAS-mutant cancer cells." (PMID 32393788, 2020). "Chelation of copper or genetic deletion of this copper-binding site inhibits autophagy and hence reduces the fitness of KRAS-induced cancers." (PMID 32420529, 2020). "The oncoprotein KRas, recognized with activating mutations in cancer, can be suppressed by activated PKC, which is proposed as a novel approach to target KRas." (PMID 33324562, 2020). "For example, although both KRAS G12V and KRAS G12R occur in >5 different cancer types, their probabilistic distributions of cancer types are different." (PMID 31925297, 2020). "Mechanistic studies in other cancer models suggest inhibition of FYN leads to greater cell death in KRAS mutant cells than in KRAS wild-type cells." (PMID 33233470, 2020). "Protein co-expression modules were linked to well-known PDAC hallmarks of cancer such as axon-guidance, EMT, oxidative phosphorylation, MYC targets and KRAS signalling, as well as potential new relationships to biological processes." (PMID 32860207, 2020). "Several miRNAs have been described recently as emerging and crucial KRAS regulators in different cancer types." (PMID 31906510, 2020). "Cancer cells, particularly those harbouring oncogenic KRAS, have been shown to be heavily dependent on glutamine for survival and proliferation." (PMID 32300895, 2020). "KRAS belongs to the Kirsten ras oncogene homolog of the RAS gene family, and was one of the first genes to be mutated in a variety of cancers." (PMID 32235004, 2020). "KRAS-mutant cancer cells rely on high levels of ROS and on a labile iron pool (LIP) to sustain their growth." (PMID 32393788, 2020). "The RAS family (KRAS, HRAS, NRAS), are frequently mutated in human cancer, approximately 25% of human malignances harbor RAS mutations." (PMID 32269211, 2020). "Mitochondrial fission driven by activating phosphorylation of DRP1 (pDRP1S616) downstream of both KRAS or BRAF pathway/s confers a growth advantage as well as metabolic shift towards a more glycolytic phenotype in various models of cancer." (PMID 33738242, 2020). "The important role of oncogenic KRAS in cancer has been met with nearly four decades of effort to develop therapeutic strategies to target aberrant KRAS function for cancer treatment." (PMID 32576853, 2020). "MCF10A cells are non-transformed and have been used extensively to model RAS signaling and mutant KRAS is often amplified in human cancer, indicating the relevance of our approach." (PMID 32398776, 2020). "Oncrasin-1 is a small molecule which was identified from a screen of KRAS mutant cancer cells and has shown specificity for KRAS mutant cell killing." (PMID 33169204, 2020). "Further, relevant to our approach here, of the three human RAS genes, KRAS, is the most enriched in rare codons and is the most commonly mutated RAS isoform in human cancers." (PMID 33296356, 2020). "We demonstrate that while the KRAS-specific DARPin degrader induces specific proteolysis of both mutant and wild type KRAS, it only inhibits proliferation of cancer cells expressing mutant KRAS in vitro and in vivo." (PMID 32591521, 2020). "We recently reported that the ectopic expression of the chemically modified MIR143-3p#12 (CM-MIR143#12) induces significant inhibition of cancer cell growth through the targeting of KRAS, AKT, and ERK in colorectal, bladder, and gastric cancer cells." (PMID 33182548, 2020).